EIF5A2 (eukaryotic translation initiation factor 5A2)
Diseases named in the same sentence as EIF5A2 in open-access papers (continued):
Sharing a sentence is not in itself a finding about the gene and the disease.
colon cancer (5 papers, 2015 to 2021). "Next we transfected colon cancer cell lines with plasmids encoding eIF5A2 to investigate the effect of eIF5A2 overexpression on tumor cells response to drugs." (PMID 26581310, 2015). "In our study, we found that eIF5A2-negative colon cancer cells were more sensitive to doxorubicin compare with the eIF5A2-positive cells." (PMID 26581310, 2015). "In conclusion, our study demonstrated that eIF5A2 promoted the chemoresistance to doxorubicin through regulation of EMT in colon cancer cells." (PMID 26581310, 2015). "Meanwhile, upregulation of eIF5A2 potentiated epithelial mesenchymal transition (EMT) in colon cancer cells." (PMID 26581310, 2015). "Our present study demonstrated that eIF5A2 promoted the chemoresistance to doxorubicin via regulation of EMT in colon cancer cells." (PMID 26581310, 2015). "We further investigated why eIF5A2 overexpression reduced doxorubicin sensitivity in colon cancer cells." (PMID 26581310, 2015). "Taken together, these results demonstrated that eIF5A2 promoted the chemoresistance to doxorubicin in colon cancer cells." (PMID 26581310, 2015). "On the contrary, overexpression of eIF5A2 reduced doxorubicin sensitivity in colon cancer cells." (PMID 26581310, 2015). "Moreover, blockade of EMT with Twist siRNA abolished eIF5A2-regulated chemoresistance in colon cancer cells." (PMID 26581310, 2015). "Moreover, eIF5A2 overexpression reduced doxorubicin sensitivity in colon cancer cells." (PMID 26581310, 2015). "Thus we hypothesized that eIF5A2 may play an important role in the chemoresistance of colon cancer cells." (PMID 26581310, 2015). "We found that eIF5A2-negtive colon cancer cells (HCT116 and HT29) were more sensitive to doxorubicin compare with the eIF5A2-positive cells (LOVO and SW480)." (PMID 26581310, 2015). "Interestingly, we observed the highest expression of eIF5A2 in LOVO cells, which were the most insensitive colon cancer cells to doxorubicin." (PMID 26581310, 2015). "Not surprisingly, eIF5A2 upregulation significantly reduced the expression of E-cadherin and enhanced vimentin expression in the four colon cancer cell lines." (PMID 26581310, 2015). "Moreover, specific downregulation of eIF5A2 could reverse the EMT and enhance chemosensitivity to doxorubicin in colon cancer cells." (PMID 26581310, 2015).
osteosarcoma (5 papers, 2021 to 2023). A usually aggressive malignant bone-forming mesenchymal neoplasm, predominantly affecting adolescents and young adults. "LncRNA GSEC promotes osteosarcoma’s proliferation, migration, and invasion by targeting the miR-588/ EIF5A2 axis." (PMID 37842058, 2023). "Liu and colleagues found that GSEC accelerated the proliferation and invasion of osteosarcoma via regulating miR-588/EIF5A2 axis." (PMID 36227151, 2022). "The lncRNA GSEC was previously reported to upregulate EIF5A2 expression via miR-588 sponging and subsequently facilitate cell proliferation, migration, and invasion capabilities in osteosarcoma." (PMID 35320929, 2021). "On the other hand, the overexpression of GSEC could promote osteosarcoma progression by inhibiting the miR-588/EIF5A2 signaling pathway." (PMID 35482720, 2022). "In osteosarcoma, GSEC boosts proliferation and metastasis through the miR-588/EIF5A2 axis with sponge activity." (PMID 34488540, 2021).
lung carcinoma (4 papers, 2015 to 2025). "The study reported that silencing of eIF5A-2 repressed cell migration and invasion in lung cancer." (PMID 35874632, 2022).
lymph node metastasis (3 papers, 2020 to 2024). "To further explore the association between EIF5A2 and lymph node metastasis, we performed a thorough analysis by compiling data on high EIF5A2 expression and lymph node (LN) metastasis status." (PMID 38770178, 2024). "Both isoforms of EIF5A have been investigated for their association with human cancer malignances, while EIF5A2 has been shown to be involved in tumor progression, poor prognosis, and lymph node metastasis." (PMID 32605067, 2020). "and eIF5A2 overexpression was related to extrathyroidal extension, lymph node metastasis, TNM staging, T classification and BRAF V600E mutation." (PMID 33200656, 2020).
pancreatic cancer (3 papers, 2020 to 2025). "Previous study has shown that targeting eIF5A2 suppressed cell proliferation in pancreatic cancer cells in vitro and in vivo." (PMID 33200656, 2020).
anaplastic thyroid carcinoma (2 papers, 2021 to 2022). "However, EIF5A2 is negatively correlated with TGFβ signaling in anaplastic thyroid carcinoma." (PMID 33827661, 2021).
gall bladder cancer (2 papers, 2021 to 2025). "Compared to normal gallbladder tissues, EIF5A2 expression is elevated in gallbladder cancer." (PMID 40964657, 2025).
glioma (2 papers, 2012 to 2021). A benign or malignant brain and spinal cord tumor that arises from glial cells (astrocytes, oligodendrocytes, ependymal cells). "In order to establish an in vitro model for further functional characterisation of the hypusine modification in gliomas, we analysed the expression of eIF-5A, eIF-5A2, DHS and DOHH in different cell lines." (PMID 22927971, 2012). "This hypothesis is substantiated by the finding that in samples of two non-glioma patients, eIF-5A, eIF-5A2 and DHS expression was mainly detectable in persisting neurons, ependymal and some other brain tissues, but rarely or not at all in astrocytes." (PMID 22927971, 2012).
liver cancer (2 papers, 2025). An epithelial or non-epithelial malignant neoplasm that arises from the liver. "Knocking down EIF5A2 can reverse EMT by inhibiting ROS pathway, thereby inhibiting liver cancer cells' invasion and metastasis." (PMID 40964657, 2025). "Overexpression of EIF5A2 can induce EMT to promote liver cancer cell metastasis, and silencing of EIF5A2 can enhance the sensitivity to 5-fluorouracil (5-FU) in liver cancer cells by blocking the p38 MAPK and JNK/c-Jun/MMP-2 signaling pathways." (PMID 40964657, 2025).
neuroblastoma (2 papers, 2022 to 2023). Neuroblastoma (NB) is the most common solid, extracranial childhood tumor. "In this study, we profiled the entire transcriptome in a human neuroblastoma cell line (SH-SY5Y cells) following the overexpression of EIF5A2, which allows for the decoding of the EIF5A2-mediated regulation of gene expression." (PMID 36750933, 2023). "We demonstrated that eight genes closely related to the UPR were downregulated in EIF5A2-OE human neuroblastoma cells (SH-SY5Y cell line)." (PMID 36750933, 2023).
oral cancer (2 papers, 2020 to 2022). "In conclusion, our findings have demonstrated that the increased expression of EIF5A2 in oral cancer patients is associated with regional lymph node metastasis and poor overall survival rate." (PMID 32605067, 2020). "The expression of EIF5A2 was investigated by IHC using tissue of primary tumor including 272 oral cancer patients." (PMID 32605067, 2020). "A multivariate analysis was used to clarify the independent prognostic role of EIF5A2 expression in oral cancer patients." (PMID 32605067, 2020). "In order to determine the EMT markers among different levels of EIF5A2 expression in the oral cancer patients, we further detected E-cadherin and beta-catenin protein expression." (PMID 32605067, 2020). "In this study, we analyzed multiple clinical parameters of 272 oral cancer patients along with EIF5A2 expression, providing evidence indicating that EIF5A2 has a potential role in oral cancer clinical prognosis." (PMID 32605067, 2020). "After adjusting for age, gender, smoking, betel quid chewing, and stage, EIF5A2 expression remained statistically significant with the overall survival of oral cancer patients (HR = 1.714, 95% CI: 1.134–2.590, p = 0.011)." (PMID 32605067, 2020). "Our results for the oral cancer patient sample studied with IHC staining demonstrated that an increase in EIF5A2 expression is significantly related to poor overall survival rate as patients with regional lymph node metastasis showed higher EIF5A2 expression." (PMID 32605067, 2020). "Although EIF5A2 has not become an invariable hallmark of cancer due to its poor expression in some lymphoma and leukemia cell lines, there is a lack of studies on the relationship between EIF5A2 expression and oral cancer." (PMID 32605067, 2020). "Therefore, with a notable correlation between EIF5A2 expression and oral cancer regional lymph node metastasis, we speculate that overexpression of EIF5A2 may result in an advanced stage of oral cancer by inducing EMT." (PMID 32605067, 2020). "In a mouse mesenchymal phenotypic oral cancer cell model, silencing eIF5A2 significantly increased the toxicity of cisplatin toward mesenchymal phenotypic oral cancer cells, without an obvious increase in side effects." (PMID 35931669, 2022). "Further, our study is the first to support that EIF5A2 may result in tumor malignancy via the EMT pathway, indicating EIF5A2 as a possible prognostic biomarker, which has important clinical significance for judging the clinical prognosis of oral cancer." (PMID 32605067, 2020).
oral squamous cell carcinoma (2 papers, 2020 to 2021). "This is consistent with the results obtained by a previous study showing that the upregulation of EIF5A2 during oral squamous cell carcinoma progression and lymph node metastasis predicted EIF5A2 as a possible new biomarker." (PMID 32605067, 2020). "Although previous research suggests EIF5A2 as a possible biomarker and therapeutic target in several cancers, the relation between oral squamous cell carcinoma (OSCC) and EIF5A2 expression remains unknown." (PMID 32605067, 2020).
ovarian tumor (2 papers, 2021). "The primary ovarian tumors were significantly reduced in mice injected with EIF5A2 KO cells than control mice as indicated by tumor weight." (PMID 33827661, 2021). "EIF5A2 copy numbers were significantly amplified in ovarian tumors as compared to normal tissues (p = 1.94E-197)." (PMID 33827661, 2021). "In the present study we provide evidence that EIF5A2 contributes to ovarian tumor growth and metastasis by promoting EMT via activation of the TGFβ pathway." (PMID 33827661, 2021). "For the first time, we demonstrated in this study that EIF5A2 contributes to ovarian tumor metastasis by promoting EMT via activation of the TGFβ pathway." (PMID 33827661, 2021). "Previous studies have illustrated that EIF5A2 is highly expressed in ovarian tumor tissues and acts as an oncogenic role in EOC patients, but the effect of EIF5A2 in CSCs and specific mechanism in EOC remains largely unclear." (PMID 33726845, 2021). "EIF5A2 promotes primary ovary tumor growth and metastasis by promoting EMT and activating the TGFβ pathway." (PMID 33827661, 2021). "Our results indicate that EIF5A2 is an important controller of ovarian tumor growth and metastasis by promoting EMT and activating the TGFβ pathway." (PMID 33827661, 2021). "Our studies indicate that EIF5A2 is a potential biomarker for diagnosis and prognosis and also an attractive drug target due to its low expression in normal tissues and high expression in ovarian tumors." (PMID 33827661, 2021). "In this study, we investigate whether EIF5A2 contributes to ovarian tumor metastasis by promoting EMT." (PMID 33827661, 2021). "Ovarian tumor sections were immunostained with EIF5A2, vimentin, and cytokeratin-7 antibodies." (PMID 33827661, 2021). "We then examined EIF5A2, EMT markers and pSMAD2 expression in primary ovarian tumors by WB." (PMID 33827661, 2021).
viral infection (2 papers, 2022 to 2023). "The eukaryotic translation initiation factor 5A1 (eIF5A1) and 5A2 (eIF5A2) are important proteins in a variety of physiological and pathophysiological processes and their function has been linked to neurodevelopmental disorders, cancer, and viral infections." (PMID 36848144, 2023). "Interestingly, a recent report shows that eIF5A2 downmodulation does not regulate global protein synthesis but it controls the expression of antiviral genes and thus depletion of eIF5A2 increases the susceptibility of cells to viral infection." (PMID 35967877, 2022). "The mouse models generated in this study are new tools useful to study human eIF5A1 and eIF5A2 function in neurological disorders, cancer, viral infections, and other diseases." (PMID 36848144, 2023).
acute myeloid leukemia (1 paper, 2021). Acute myeloid leukemia (AML) is a group of neoplasms arising from precursor cells committed to the myeloid cell-line differentiation. "A recent study indicated that circ_0058058 increased EIF5A2 expression through miR-4319 to accelerate cell proliferation, invasion, and migration in hematological malignancy acute myeloid leukemia (AML)." (PMID 34930344, 2021).
chronic pancreatitis (1 paper, 2024). A chronic inflammatory process causing damage and fibrosis of the pancreatic parenchyma. "Moreover, TGF-β1-induced MIAT contributes to the activation of pancreatic stellate cells in chronic pancreatitis and proximal tubule epithelial cells in renal interstitial fibrosis by targeting miR-216a-3p/COX-2 or miR-145/EIF5A2 axes, respectively." (PMID 39379100, 2024).
Cirrhosis (1 paper, 2023). A chronic disorder of the liver in which liver tissue becomes scarred and is partially replaced by regenerative nodules and fibrotic tissue resulting in loss of liver function. "Accordingly, we found that decreased miR-146a-5p as well as increased EIF5A2 was found in patients with cirrhosis in comparison with the healthy controls." (PMID 37598186, 2023). "Additionally, a negative correlation between EIF5A2 and miR-146a-5p was found in HSCs and patients with cirrhosis." (PMID 37598186, 2023).
colorectal tumors (1 paper, 2016). "We have observed a significant increase in eIF5A2 mRNA levels in colorectal tumors." (PMID 27433286, 2016).
head and neck squamous cell carcinoma (1 paper, 2025). A squamous cell carcinoma that arises from any of the following anatomic sites: lip and oral cavity, nasal cavity, paranasal sinuses, pharynx, larynx, and salivary glands. "Cox regression analysis demonstrated that high EIF5A2 expression was associated with unfavorable overall survival (OS) and disease-specific survival (DSS) in head and neck squamous cell carcinoma (HNSC), brain lower grade glioma (LGG), and LIHC." (PMID 40964657, 2025).
Infertility (1 paper, 2022). "EIF5A2 has been reported as a candidate gene for age at sexual maturity in Indian Buffalo and for infertility in human." (PMID 35158654, 2022).
liver fibrosis (1 paper, 2023). "Collectively, exosomal miR-146a-5p from Sal-treated hepatocytes inhibits HSC activation and liver fibrosis, at least in part, by suppressing EIF5A2 and EMT process." (PMID 37598186, 2023). "In conclusion, exosomal miR-146a-5p from Sal-treated hepatocytes inhibits HSC activation and liver fibrosis, at least in part, via suppressing EIF5A2 and EMT process." (PMID 37598186, 2023).
lung adenocarcinoma (1 paper, 2023). A carcinoma that arises from the lung and is characterized by the presence of malignant glandular epithelial cells. "In the present study we have addressed the role of eIF-5A2 in lung adenocarcinoma (LUAD), the most common histological type of non-small cell lung cancer (NSCLC)." (PMID 36915194, 2023). "We have evaluated the use of eIF-5A2 gene as prognosis marker in lung adenocarcinoma (LUAD) patients and validated in immunocompromised mice." (PMID 36915194, 2023). "Human translation factor eIF-5A2 isoform is frequently overexpressed in lung adenocarcinoma." (PMID 36915194, 2023).
lung squamous cell carcinoma (1 paper, 2025). "The frequency of EIF5A2 gene alterations was the highest in lung squamous cell carcinoma (LUSC)." (PMID 40964657, 2025).
metastatic cancers (1 paper, 2020). A carcinoma which has spread from the original site of growth to another anatomic site. "The human eIF5A-1 isoform is abundant and implicated in some cancer types; the eIF5A-2 isoform is absent in most cells but becomes overexpressed in many metastatic cancers." (PMID 33379337, 2020).
mucinous carcinomas (1 paper, 2021). "However, it remains to be further analyzed whether there is correlation between EIF5A2 expression level and the different stages and/or grades in other types of OC including clear cell, endometrioid, and mucinous carcinomas." (PMID 33827661, 2021).
papillary thyroid cancer (1 paper, 2020). "However, the potential role of eIF5A2 in human papillary thyroid cancer (PTC) is unknown." (PMID 33200656, 2020).
primary immunodeficiency (1 paper, 2025). "High EIF5A2 expression was associated with several pathways, including cell cycle, proteasome, DNA replication, primary immunodeficiency and oocyte meiosis." (PMID 40964657, 2025). "To clarify the biological process of EIF5A2 in LIHC, we conducted GSEA functional enrichment analysis and found that the group with high EIF5A2 expression participated in the following pathways: cell cycle, proteasome, DNA replication, primary immunodeficiency and oocyte meiosis." (PMID 40964657, 2025).
prostate tumors (1 paper, 2021). "Our results suggest that AR positively regulates eIF5A2 expression in androgen-dependent cells, and stimulation of AR expression and signaling in prostate tumors promotes PCa metastasis by EMT induction and upregulation of eIF5A2." (PMID 34864817, 2021).
serous carcinomas (1 paper, 2021). "We further examined the correlation of EIF5A2 copy number and mRNA expression in two different datasets of TCGA database including 629 serous carcinomas from Firehose Legacy and 608 from PanCancer Atlas." (PMID 33827661, 2021).
serous ovarian carcinomas (1 paper, 2021). "In the present study, we analyzed the expression of EIF5A2 in high grade serous ovarian carcinoma from several databases, and found EIF5A2 was associated with tumor metastasis and poor patient survival." (PMID 33827661, 2021).
thyroid carcinoma (1 paper, 2022). "Moreover, EIF5A2 could modulate TGF-/Smad2/3 signal in thyroid carcinoma." (PMID 35064108, 2022).
urothelial carcinoma of the bladder (1 paper, 2020). "In pTa/pT1 urothelial carcinoma of the bladder, patients with high eIF5A2 protein levels in carcinoma tissues had shorter mean recurrence-free survival time and mean progression-free survival time than that of patients with low expression in carcinoma tissues." (PMID 32368188, 2020). "Urothelial carcinoma of the bladder is the most common histopathologic type of bladder cancer (BC), and the expression of eIF5A2 protein serves as a useful molecular marker to predict outcome in patients with urothelial carcinoma of the bladder, after patients were treated with radical cystectomy." (PMID 32368188, 2020).